BDNF (brain derived neurotrophic factor)
Diseases named in the same sentence as BDNF in open-access papers (continued):
Sharing a sentence is not in itself a finding about the gene and the disease.
Alzheimer disease (continued). "Elevated levels of H3k9me1 in mouse models of Alzheimer's disease (AD) leads to the downregulation of BDNF (brain-derived neurotrophic factor)." (PMID 34344473, 2021). "BDNF plays a critical role in multiple pathological conditions, such as Alzheimer’s disease, Huntington’s disease, and psychiatric disorders." (PMID 32570881, 2020). "Despite BDNF showing potential neuroprotective effects in stroke, traumatic brain injury, and Alzheimer’s disease, the therapeutic delivery of BDNF has many obstacles related to its short in vivo half-life and uncertain BBB permeability." (PMID 33177978, 2020). "A preclinical study stated that the dysregulation of BDNF signaling is involved in several neurodegenerative disorders, including Alzheimer’s disease, and leads to a deficit in age-related learning." (PMID 32397504, 2020). "Several clinical studies have shown changes in blood concentration of BDNF in patients with neuropsychiatric disorders such as major depression, schizophrenia and Alzheimer’s disease." (PMID 32397504, 2020). "For instance, enhancement of BDNF expression in the hippocampus has been a promising strategy to treat Alzheimer’s disease in mouse models." (PMID 32489703, 2020). "Combined mimic exercise and elevating BDNF levels to enhance adult neurogenesis improve cognitive function and protect against subsequent neuronal cell death in an Alzheimer disease (AD) mouse model." (PMID 33537297, 2020). "APP protein plays a central role in the development of Alzheimer’s disease; its expression, metabolism, splicing and secretion have been demonstrated to be regulated by ligands of the membrane tyrosine kinase receptors like BDNF." (PMID 32397504, 2020). "Abnormal expression levels of BDNF have been reported in the postmortem brains of Alzheimer’s disease, Parkinson’s disease, Huntington’s disease, depression, and schizophrenia." (PMID 32894176, 2020). "Michalski B, Fahnestock M. Pro-brain-derived neurotrophic factor is decreased in parietal cortex in Alzheimer’s disease." (PMID 32876194, 2020). "In support of this, castration decreased BDNF levels in the hippocampus of male rats, and testosterone implants increased hippocampal BDNF in a transgenic male mouse model of Alzheimer’s disease (SAMP8)." (PMID 32028656, 2020). "Expression of BDNF has also been found to be reduced in patients with Alzheimer’s disease, Parkinson’s disease, and Huntington’s disease indicating its importance the healthy adult brain." (PMID 30867560, 2020). "In an Alzheimer’s disease transgenic model, quetiapine attenuated the decrease in number of BDNF positive cells in basolateral amygdala and hippocampus of Alzheimer’s disease mice." (PMID 32973585, 2020). "In a streptozotocin-induced astrocytotoxicity model for Alzheimer’s disease, memantine ameliorated BDNF and GDNF decline in astrocytes along with phosphorylation of IRS-1, Akt, and GSK-3α/β." (PMID 32782018, 2020). "Extrasynaptic NMDAR activation and dysfunctional BDNF signaling are early hallmarks of neurodegenerative diseases such as Alzheimer's disease (AD), Huntington's disease (HD), and Parkinson's disease (PD)." (PMID 32849999, 2020). "A decrease of BDNF production has been found in many neurodegenerative diseases, including Alzheimer’s disease (AD) and Parkinson’s disease (PD)." (PMID 32560430, 2020). "Such information is important because Alzheimer’s disease (AD) has been associated with lower serum levels of IGF-1 and BDNF." (PMID 32192537, 2020). "Reduced levels of BDNF have been reported not only under normal aging conditions but also in pathological conditions including Huntington (HT), Alzheimer’s disease (AD), and Parkinson’s disease." (PMID 31440144, 2019). "We focused on 12 CpG sites in promoter IV of the BDNF gene as this region has been previously reported as differentially methylated in Alzheimer’s disease and other neurological conditions." (PMID 32038165, 2019).
Alzheimer disease (continued). "Brain-derived neurotrophic factor (BDNF) plays crucial roles in memory impairments including Alzheimer’s disease (AD)." (PMID 31186474, 2019). "Previous in vivo studies have also indicated that LIPUS treatment can induce the expression of BDNF and alleviate Alzheimer’s disease and neuronal degeneration of stroke-induced brain injury." (PMID 31635269, 2019). "A direct connection between exercise, elevated brain BDNF levels, and rescue of synaptic function in Alzheimer’s disease has been described recently." (PMID 31017891, 2019). "It has been documented that BDNF expression is reduced in the brains of Alzheimer’s disease (AD) patients." (PMID 31315045, 2019). "PA improves cognition in a mouse model of Alzheimer’s disease (AD), stimulating neurogenesis and the simultaneous increase of both BDNF and FNDC5." (PMID 31533339, 2019). "In the following sections, we will discuss the role of BDNF in neurodegenerative disorders, focusing of Alzheimer’s disease, Parkinson’s disease, and epilepsy." (PMID 30117106, 2019). "The same trend has been found in subjects with Alzheimer’s disease where BDNF mRNA, its precursor (proBDNF), and mature protein levels significantly decrease, while NGF mRNA does not change, and the NGF precursor molecule proNGF increases." (PMID 30939824, 2019). "Targeting of brain BDNF mRNAs with miRNA‐206 was first demonstrated in Tg2576 Alzheimer disease transgenic mice." (PMID 30761261, 2019). "In animal models of the disease and in humans, the levels of NGF and BDNF follow different trajectories in brain areas affected in Alzheimer’s disease." (PMID 30939824, 2019). "In these studies, treatment with valproic acid reversed an impairment of BDNF expression induced in animal models of bipolar disorder, Alzheimer’s disease, or facial nerve transection." (PMID 31044578, 2019). "The objective of the present study was to investigate the effect of an aloe polymannose multinutrient complex (APMC) on pro brain-derived neurotrophic factor (BDNF) and mature BDNF in persons with moderate to severe Alzheimer's dementia." (PMID 30895275, 2018). "Previously published studies have demonstrated the successful use of adenoviral constructs for BDNF overexpression in Alzheimer’s disease, Huntington’s disease, and Friedrich’s motor ataxia." (PMID 30081596, 2018). "Elevated expression of BDNF is implicated in the pathogenesis of epilepsy and chronic pain sensitization whereas the neurotrophic property of BDNF is expected to restore neurodegenerative disorders such as Parkinson’s disease and Alzheimer’s disease." (PMID 30356026, 2018). "Decreased BDNF levels were reported in Alzheimer's disease, neurodegenerative and psychiatric disorders, stroke, and brain aging, just to name a few." (PMID 29556248, 2018). "It has been shown that the expression of BDNF mRNA and the level of mature BDNF significantly decreases in the hippocampus and the cerebral cortex during the development of Alzheimer’s disease." (PMID 30081596, 2018). "Activation of DRD5 also protected dopaminergic neurons in a PD rat model, promoted neurogenesis in an Alzheimer’s disease mouse model and regulated BDNF expression in the rodent brain." (PMID 30459594, 2018). "In Alzheimer’s disease, known for its neurodegenerative process and cognitive decline, BDNF levels in the brain and also in the blood were found to be significantly reduced." (PMID 29995884, 2018). "In the case of recombinant BDNF application in Alzheimer’s disease and Parkinson’s disease, significant inhibition of neurodegenerative processes in the brain were observed." (PMID 30081596, 2018). "Serum concentrations of BDNF have been demonstrated to be stage-dependent, such that increased serum levels of BDNF have been found in early-stage Alzheimer's disease (AD), while decreased serum BDNF levels occur in late-stage AD." (PMID 30524358, 2018).
Alzheimer disease (continued). "In Alzheimer’s disease (AD), BDNF signaling is known to be impaired, partially because amyloid β (Aβ) induces truncation of BDNF main receptor, TrkB-full length (TrkB-FL)." (PMID 29695962, 2018). "Studies on animals and on humans affected by diabetes and Alzheimer's disease seem to suggest a biphasic behaviour of BDNF with increased level in the first phase of disease and decreased level in a later phase." (PMID 28161695, 2017). "Changes in NGF and BDNF levels in the serum have been reported for central neurodegenerative diseases such as Alzheimer’s disease and Parkinson’s." (PMID 28068360, 2017). "In a recent study, chronic treatment with Perilla oil (500 mg/kg/day by gastric gavage) normalized the decrease in BDNF protein levels in an animal model of Alzheimer's disease." (PMID 29464125, 2017). "MiR-206 upregulation, as observed in a mouse model of Alzheimer's disease, downregulates the neuroprotective protein brain-derived neurotrophic factor, which likely contributes to disease pathogenesis." (PMID 27893428, 2017). "In parallel, biological markers involved in both hippocampal neurogenesis and Alzheimer’s disease, such as BDNF, VEGFA and IGF-1, were evaluated in aged mice." (PMID 28218311, 2017). "In Alzheimer's disease mouse model, HT chronic treatment (10 mg/day by gavage for 14 days) attenuated the spatio-cognitive deficits and normalized the hippocampal BDNF mRNA levels." (PMID 29464125, 2017). "In the following sections, due to limited references to other neurological diseases, only histone modifications of the BDNF gene in Huntington’s disease and Alzheimer’s disease are discussed." (PMID 28272318, 2017). "In the hippocampus of a mouse model of Alzheimer's disease, induced by AlCl3, cotreatment with caffeine (1.5 mg/day by gavage) partially prevented the decrease in BDNF gene expression, while the pretreatment completely normalized the impairment." (PMID 29464125, 2017). "The nerve growth factor (NGF) and brain-derived neurotrophic factor (BDNF) have been widely studied with respect to their role in the pathogenesis of Alzheimer’s disease." (PMID 28974056, 2017). "It has been suggested that fucoxanthin exhibited great therapeutic efficacy in Alzheimer’s disease by inhibiting acetylcholinesterase (AChE) and increasing brain-derived neurotrophic factor (BDNF) expression." (PMID 28429775, 2017). "BDNF replacement therapy is currently being investigated in animal models and clinical studies, including Huntington’s disease, Alzheimer’s disease and depression." (PMID 29097744, 2017). "The main problem is that studies take into consideration different animal models mimicking different kinds of diseases, from Alzheimer's disease to stroke, thus making further results mandatory to confirm the supposed effect on BDNF." (PMID 29464125, 2017). "We found that BDNF protein levels are lower in human AD hippocampus, confirming the previous report that precursor form of BDNF and m-BDNF are decreased in the pre-clinical stages of Alzheimer’s disease." (PMID 28569173, 2017). "There are lower levels of BDNF in the brain tissues of people with Alzheimer’s disease, and it has already been known that BDNF is anti-apoptotic, also plays role in progression of cancer." (PMID 27875990, 2016). "The salient pathological feature in Alzheimer's disease (AD) is hippocampal network degeneration, and BDNF has been shown to play a protective role in attenuating amyloid-related toxicity." (PMID 27494844, 2016). "Brain-derived neurotrophic factor (BDNF) has been suggested to reduce amyloid-β neurotoxicity in Alzheimer's disease." (PMID 27924190, 2016). "In transgenic mouse models of Alzheimer's disease, an impaired retrograde transport of endocytosed BDNF was described by Poon and colleagues." (PMID 26881108, 2016).
Alzheimer disease (continued). "Recent studies have shown that brain-derived neurotrophic factor (BDNF) is associated with tooth loss or soft diet in young animal model, and that BDNF expression is decreased in patients with Alzheimer’s disease." (PMID 27919226, 2016). "Blood BDNF derives primarily from the brain, and has been observed in several diseases accompanied by inflammation—rapid cycling bipolar disorder, Alzheimer’s disease, and fibromyalgia." (PMID 27352030, 2016). "MicroRNA-206, which suppresses the expression of brain-derived neurotrophic factor, is known to be elevated in the brains of Alzheimer’s disease (AD) patients." (PMID 26842588, 2016). "In animal models of Alzheimer's disease, the expression of growth factors, such as BDNF, reinstated hippocampal function following physical activity by promoting neurogenesis, angiogenesis, and synaptic plasticity." (PMID 26146460, 2015). "There is increasing evidence that brain-derived neurotrophic factor (BDNF) plays a crucial role in Alzheimer’s disease (AD) pathology." (PMID 25852506, 2015). "A more recent research reported both increased proNGF and decreased BDNF levels in postmortem brain samples of subjects with several tauopathies (non-Alzheimer's disease dementias) as compared to age matched controls." (PMID 26137470, 2015). "It has been shown that CeO2 NPs modulate the brain-derived neurotrophic factor (BDNF) pathway in human Alzheimer’s disease models in order to trigger neuronal survival." (PMID 25625406, 2015). "Our group administered antagomiR of miR-206 in the Alzheimer's disease transgenic mouse model, and showed a cognitive enhancing effect by increasing the BDNF." (PMID 24959881, 2014). "Although BDNF is widely distributed in the human brain, its expression is reduced in neurodegenerative disorders including Alzheimer's disease, Huntington's disease and Parkinson disease." (PMID 24760076, 2014). "Currently, activation of inflammatory mediators and reduction of BDNF have been proposed as the potential mechanism for Alzheimer’s disease." (PMID 24422705, 2014). "Alzheimer’s disease (AD) brains demonstrate decreased levels of brain-derived neurotrophic factor (BDNF) and increased levels of β-amyloid peptide (Aβ), which is neurotoxic." (PMID 25371750, 2014). "Recent studies have highlighted the potential of targeting BDNF/TrkB signaling for the treatment of neurodegenerative diseases such as Alzheimer disease (AD)." (PMID 24614170, 2014). "Recent studies have shown that AChE inhibitors significantly increase levels of brain-derived neurotrophic factor (BDNF) in serum of Alzheimer’s disease patients and in mice after transient cerebral ischemia and reperfusion." (PMID 24595240, 2014). "The association between polymorphisms rs6265 and rs2030324 in brain-derived neurotrophic factor (BDNF) and Alzheimer’s disease (AD) has been widely reported, but the results remain controversial." (PMID 24733169, 2014). "On the other hand, a 2-fold elevation in endogenous BDNF by the suppression of miR-206, a direct negative regulator of BDNF levels, alleviates disease phenotype in a mouse model of Alzheimer’s disease." (PMID 25279294, 2014). "Brain derived neurotrophic factor (BDNF) has been known to play an important role in various mental disorders or diseases such as Alzheimer's disease (AD)." (PMID 25364831, 2014). "Common among these BDNF-related disorders, such as Alzheimer's disease (AD), Huntington disease (HD), is the irregular trafficking of dense-core vesicles containing BDNF, as well as activity-dependent BDNF release from those vesicles." (PMID 24639629, 2014). "The association of genes such as brain-derived neurotrophic factor (BDNF) and apolipoprotein-E (ApoE) with cognitive decline and late-onset Alzheimer’s disease (AD) has been investigated." (PMID 25339899, 2014).
Alzheimer disease (continued). "Consistent evidence indicates the involvement of the brain-derived neurotrophic factor (BDNF) in neurodegenerative disorders such as Alzheimer's disease (AD) and Parkinson's disease (PD)." (PMID 24024214, 2013). "These new results can be relevant for schizophrenia, Parkinson’s disease and Alzheimer’s disease, as they provide a correlation between diminished BDNF-TrkB signaling and the observed declines in GluR1 and SAP97 proteins in these diseases." (PMID 23460828, 2013). "Transfers of the BDNF gene have been of therapeutic value for Huntington’s disease and Alzheimer’s disease." (PMID 24300402, 2013). "Reduced BDNF levels have been detected in the brains of Alzheimer’s disease (AD) patients but the exact role of BDNF in the pathophysiology of the disorder remains obscure." (PMID 23844236, 2013). "For example, it has been reported that the frontal cortex of patients with Alzheimer's disease has decreased BDNF and TrkB.FL expression accompanied by increased truncated TrkB expression." (PMID 22761934, 2012). "In Alzheimer's disease patients, BDNF mRNA was reduced 50% in nuclei of the basal forebrain, the origin of the cholinergic neurons that innervate the cortex and hippocampus, and a region associated with the cognitive deterioration seen in Alzheimer's." (PMID 22720171, 2012). "Both forms have now been shown to be reduced in Alzheimer’s disease, with a reduction in mature BDNF of 23% reported in frontal cortex." (PMID 22654716, 2011). "In particular there have been a number of studies on the involvement of nerve growth factor (NGF) and brain derived neurotrophic factor (BDNF) in the development of Alzheimer’s disease." (PMID 22654716, 2011). "The entorhinal cortex is one of the first areas affected in Alzheimer’s disease; TrkB receptors are expressed there and it is a major provider of BDNF through its input to the hippocampus." (PMID 22654716, 2011). "Evidence to support this includes substantially reduced BDNF mRNA levels in Alzheimer’s disease hippocampus and parietal cortex and decreased protein levels of BDNF in entorhinal cortex, hippocampus, temporal, frontal and parietal cortex." (PMID 22654716, 2011). "BDNF administration into the entorhinal cortex in animal models of Alzheimer’s disease recently produced promising therapeutic results." (PMID 22654716, 2011). "This contrasts with Alzheimer's disease, where BDNF levels are usually reduced." (PMID 41084412, 2026). "In Alzheimer’s disease (AD), brain levels of Brain-derived neurotrophic factor (BDNF) are reduced." (PMID 41831005, 2026). "Indeed, saxagliptin has been shown to increase BDNF levels in the specific indications of PD and Alzheimer disease (AD)." (PMID 39904872, 2025). "TrkB agonists, in addition to BDNF stabilizing agents, and other agent classes are insistingly reported to prospectively augment therapeutic outcomes of dopamine replacement in PD, and AAV delivery of BDNF to potentially augment amyloid-clearing mechanisms in the treatment of Alzheimer’s disease." (PMID 40362507, 2025). "Consequently, modulating the BDNF signaling pathway holds promise for ameliorating cognitive deficits in individuals afflicted with Alzheimer's disease 137-139." (PMID 39744428, 2025). "Notably, in chronic inflammation, such as Alzheimer’s disease, both 5-HT2b and BDNF levels are elevated, paradoxically contributing to neurotoxicity as BDNF released near amyloid plaques promotes TNF-α and glutamate release." (PMID 41511349, 2025). "The Brain-derived neurotrophic factor (BDNF) signaling pathway plays a role in neuronal survival, growth, and synaptic plasticity; interventions targeting this pathway have shown promise for improving cognitive decline in Alzheimer’s disease patients." (PMID 39951434, 2025).